SPATA21 (spermatogenesis associated 21)
Description:
Involved in the differentiation of haploid spermatids.
Synonyms: spergen-2; spergen2
Tractability: No criterion of Open Targets' tractability assessment is met for any kind of drug.
Gene: Protein-coding gene on chromosome 1 (16,387,117 to 16,437,424, reverse strand). Ensembl gene ENSG00000187144.
Subcellular location (Human Protein Atlas): Cytosol; Vesicles
Gene Ontology:
Molecular function: calcium ion binding
Genetic constraint (gnomAD): Loss-of-function variants: 44 observed, 53.97 expected, observed/expected ratio (o/e) 0.82, 90% interval 0.64 to 1.05. The upper end of that interval is the gene's LOEUF score, 1.05, which puts it in group 4 of 6, group 1 being the genes least tolerant of losing a copy. Missense variants: 585 observed, 591.67 expected, observed/expected ratio (o/e) 0.99, 90% interval 0.92 to 1.06. Synonymous variants: 234 observed, 232.95 expected, observed/expected ratio (o/e) 1, 90% interval 0.9 to 1.12.
Homologues: Orthologues: chimpanzee SPATA21 (99% identical), macaque SPATA21 (90% identical), dog SPATA21 (68% identical), rabbit SPATA21 (66% identical), rat Spata21 (66% identical), mouse Spata21 (66% identical), zebrafish si:ch211-197n1.2 (7% identical), Drosophila melanogaster TpnC47D (2% identical), Drosophila melanogaster TpnC73F (2% identical), Drosophila melanogaster TpnC41C (2% identical). Paralogues in human: EFCAB6 (17% identical), PHF24 (7% identical), CAPS2 (7% identical), CAPSL (5% identical), CAPS (3% identical).
Diseases named in the same sentence as SPATA21 in open-access papers:
SPATA21 is named in the same sentence as 2 diseases in open-access papers, as found by Europe PMC text mining. Sharing a sentence is not in itself a finding about the gene and the disease. The quoted sentences say what the papers report.
idiopathic scoliosis (1 paper, 2021). A scoliosis with no known cause. "A gene-based association study has shown that SPATA21 is one of several genes implicated in adolescent idiopathic scoliosis." (PMID 33494820, 2021).
tumor (1 paper, 2022). "In addition, genes such as C11orf34 and SPATA21, which ranked among the top 15 most significant, have rarely been reported to be related to tumor development." (PMID 36292798, 2022).